CD36 (CD36 molecule (CD36 blood group))
Diseases named in the same sentence as CD36 in open-access papers (continued):
Sharing a sentence is not in itself a finding about the gene and the disease.
tumor (continued). "Among these, CD273 and CD146 may indeed be MSC-specific, whereas CD36 (a receptor for thrombospondin-1), CD200 (also expressed on tumor cells), CD274 (PDL-1), and CD248 (endosialin) are also expressed in fibroblasts, often in a tumor context." (PMID 39201399, 2024). "VT1021 is a cyclic peptide that inhibits tumor growth by inducing the anti-angiogenic factor thrombospondin-1 (TSP-1) in myeloid-derived suppressor cells (MDSCs), thereby promoting TME modulation by simultaneously targeting CD36 and CD47." (PMID 39624081, 2024). "Last but not least, CD36 plays a key role in immune evasion, maintaining immunosuppressive regulatory T cells and pro-tumorigenic M2 macrophages, suppressing tumor-infiltrating CD8+ T cells." (PMID 39627379, 2024). "Tumor-supporting activity is related to facilitating tumor invasion, proliferation and migration (mediated by CD204, CD206, CXCL16, stabilin-1, and RAGE), M2-like TAM polarization (by CD36, LOX-1, CXCL16, CD163, and RAGE), and tumor angiogenesis (by CD68, Dectin-1, and RAGE)." (PMID 39516356, 2024). "Notably, the CD36-mediated lipid uptake in these TAMs further promotes their differentiation into TAM-M2 cells, which support tumor growth." (PMID 39227970, 2024). "Research has demonstrated that CD36 facilitates the absorption of fatty acids by CD8 T cells in TME that have invaded tumors, inducing lipid peroxide and ferroptosis, resulting in reduced cytotoxic cytokine generation and impaired anti-tumor capacity." (PMID 39192972, 2024). "The spatial imaging data show that cells in tumor-involved sentinel LNs exhibit a higher probability of CD36 expression than cells from control LNs, but this was not statistically significant." (PMID 39062552, 2024). "First, to determine whether MIF from tumor cells or CD36+ CAFs mediates the regulation of CD33+ MDSC expansion, human or murine CD36+ CAFs were isolated from primary human HBV-related or murine HCC tumors." (PMID 36878933, 2023). "CD36 controls the uptake of fatty acids, and CPT1A mainly mediates fat oxidation in tumor cells." (PMID 37207149, 2023). "CD36, FATPs, and VLDLR expression are upregulated in tumor-activated PMN-MDSCs." (PMID 37700339, 2023). "CD36, a scavenger receptor expressed in multiple cell types in TME, especially effector T cells, Tregs, dendritic cells and myeloid cells, has been demonstrated to be involved in regulating anti-tumor immune response through different mechanisms." (PMID 37085798, 2023). "CD36 mediates the uptake of fatty acids by tumor-infiltrating CD8+T cells, induces lipid peroxidation and ferroptosis, and leads to reduced cytotoxic cytokine production and reduced anti-tumor ability." (PMID 37600785, 2023). "In fact, among those patients whose primary tumor was positive for cells bearing the CD14/CD36/PANK signature, the frequency of patients who did not later develop metastasis was zero." (PMID 37427108, 2023). "In summary, the clarified role of CD36+ CD8+ T cells may be the key to predict the response to targeted therapy and prognosis of tumor patients." (PMID 37085798, 2023). "Moreover, MALAT1 upregulated the expression of CD36 and liposynthases (PPARγ, PGC1α, SREBP-1C, FAS, and ACC), enhancing unsaturated fatty acid synthesis and uptake, thereby promoting tumor cell progression." (PMID 37533434, 2023). "Moreover, upregulation of CD36 in CD8+ T cells leads to excessive lipid accumulation, which impairs secretion of anti-tumor factors such as IFN-γ and TNF-α, ultimately suppressing their anti-tumor efficacy." (PMID 37700339, 2023). "Considering this accumulated data, although the mechanisms of CD36 overexpression in CRC cases are incompletely deciphered, CD36 inhibition could represent a new therapeutic target for tumor progression limitation." (PMID 37760840, 2023). "Not coincidentally, it has been shown that CD36 expression is added in tumor-infiltrating CD8+ lymphocytes (CD8+-TILs)." (PMID 36845720, 2023).
tumor (continued). "We found that the Arf1‐ablated tumor cells released HMGB1, oxidized low‐density lipoprotein (oxLDL), and genomic DNA, which might together bind to co‐receptors complex of the CD36/TLR2/TLR6 on the dendritic cell surface." (PMID 37786300, 2023). "We next examined the association between the three model genes (CD36, BATF2 and MYB) and immunotherapy response using datasets composed of pre-treated tumor biopsies from responders and non-responders in the TIGER database." (PMID 37781029, 2023). "What’s more, CD36 inhibitors could reduce the growth of oral SCC cells and inhibited lipid droplet (LD) formation, tumor progression, and metastasis." (PMID 36185215, 2022). "We found that CD36 expression in tumor cells did not change after they were co-cultured with fibroblasts." (PMID 36439884, 2022). "In addition, the CD36, LIMP-2, Emp sequence homologous (CLESH) structural domain can regulate tumor angiogenesis by interacting with the TSP-1 repeat domain 2 (TSR)." (PMID 36354702, 2022). "ACLY, ACLS4, ACSL5, SCD1, FABP1, FABP6, and CPT1A were all found to be substantially expressed in tumor tissue, although CD36, FABP3, and FABP4 were not." (PMID 35625633, 2022). "NMIBC tumor samples show increased expression of the FA transporters FATP4, CD36 and ACSL1." (PMID 36568966, 2022). "On the other hand, histological analysis revealed no significant change in tumor cell apoptosis but noted a reduction in tumor cell proliferation and angiogenesis in Cd36−/− mice compared with WT mice." (PMID 36184646, 2022). "CD36 is expressed in FBs of normal mammary glands, where normal mammary FBs are known to exert anti-tumor functions through paracrine signaling." (PMID 36361532, 2022). "As CD36 promotes uptake and accumulation of oxidized-lipids and thereby T-cell dysfunctions, its systemic or CD8+ T cell-specific deletion slows down tumor growth, and rejuvenates antitumor functions of infiltrated CD8+ T cells by preventing oxidized LDL-dependent lipid peroxidation." (PMID 35945203, 2022). "Treg-specific deletion of CD36 selectively impairs intratumoral Tregs and reduces tumor burden without overt autoimmunity." (PMID 36248808, 2022). "CD36 expression was negative in 25 tumor samples examined; weak expression was found in 8 tumor samples, whereas a positive expression was present in 4 tumor samples." (PMID 36556492, 2022). "In addition, several studies suggested CD36-mediated lipid metabolism functions in the TME, leading to immune tolerance and tumor growth." (PMID 36184646, 2022). "Moreover, outside of the tumor, splenic CD8 T cells from lean and obese mice secreted similar levels of IFN-γ, TNF, and GzmB and expressed similar levels of CD69, CD44, CD36, Eomes, and T-bet." (PMID 35103755, 2022). "However, the overexpression of CD36 induces LPO and triggers the ferroptosis of CD8+ T cells, leading to a decrease in the anti-tumor effectors IFN-γ and TNF-α; this accelerates tumor progression and results in poor prognosis." (PMID 35372083, 2022). "The distribution of patient characteristics was well-balanced between patients with CD36-positive and CD36-negative tumours, including pathological stage, histology, and type of chemotherapy." (PMID 35159947, 2022). "Peripheral CD36 and EMAP II coexpression in NHL patients suggests that EMAP II expression might regulate tumor dissemination and identify NHL patients with more aggressive diseases." (PMID 36132984, 2022). "Moreover, CD36 binds and recognizes thrombospondin-1 (TSP-1), an extracellular matrix protein that was shown to play a multifaceted role in cancer as part of the tumor microenvironment." (PMID 35054787, 2022).
tumor (continued). "This evidence calls for the study of the role of CD36 in other normal cells located in the TME and suggests that CD36 targeting may elicit anti-tumor responses by multiple mechanisms." (PMID 36568966, 2022). "For example, in glioma cells, the mechanism of the inhibitory effect of vasopressor (Vstat120) on tumor cell growth and angiogenesis relies on the binding of the TSR sequence therein to the CLESH structural domain in CD36 expressed on microvascular endothelial cells (MVECs)." (PMID 36354702, 2022). "Although the knockout of CD36 reduces FOXP3+ Treg cells within tumours, the preservation of peroxisome proliferation activation receptor-β (PPAR-β) signal-dependent mitochondrial adaptability leads to the inhibition of tumour growth." (PMID 36569832, 2022). "Tumor-supporting activity mediated by macrophage SRs includes regulation of tumor invasion, proliferation and migration (for CD204, CD206, CXCL16, Stabilin-1, and RAGE), as well as M2-like TAM polarization (for CD36, LOX-1, CXCL16, CD 163, and RAGE) and tumor angiogenesis (for CD68, Dectin-1, RAGE)." (PMID 36686729, 2022). "CD36-mediated uptake of fatty acids in CD8+T cells induces lipid peroxidation and ferroptosis, which contributes to reduced cytotoxic cytokine production and impaired anti-tumor ability." (PMID 36003368, 2022). "The expression of CD36, PTGR1, SUCLG2, CPT2 and ELOVL6 were downregulated in tumor tissues." (PMID 36568396, 2022). "This migratory behavior may be enhanced following concomitant expression of ALDH1A1 and CD36 expression induced by environmental factors, such as rich LPA present within the tumor microenvironment." (PMID 36497140, 2022). "Therefore, targeting CD36 in Tregs probably inhibits metabolic fitness of Tregs in the TME and improves tumor prognosis." (PMID 35062950, 2022). "We discovered that CD36-dependent non-dividing, metastasis-initiating tumour cells require mitochondrial m5C to activate invasion and dissemination." (PMID 35768510, 2022). "However, DLBCL clusters that correlated with tumor-conditioned monocytes highly expressed CD64, CD36, and S100A9 and thus presented similarities with IFNγ in-vitro polarized macrophages." (PMID 34975843, 2021). "On the whole, the expression of CD36 has poor implications in cancer, and while CD36 has gained significant attention in recent years, its role in tumor vasculature and cancer progression is still not fully understood." (PMID 34215227, 2021). "CD36 and FABP4 inhibition induces apoptosis in tumour cells." (PMID 34561446, 2021). "CD36 inhibition using either anti-CD36 monoclonal antibodies (mAbs) or oleic acid analog sulfo-n-succinimidyl oleate (SSO), which irreversibly binds CD36, have proven efficacy in preventing tumor growth and metastasis in preclinical models." (PMID 34203535, 2021). "In this study, as CD36 in Tregs was important to suppress the anticancer immunity, a monoclonal antibody that blocked CD36 from bonding to fatty acids and to oxidized LDLs induced apoptosis of Treg cells while promoting the accumulation of CD8+ T cells in the tumor." (PMID 33717139, 2021). "Furthermore, immunocytochemistry (ICC) of the PSCA, CD36, and SPINK1 proteins confirms their colocalization in the BrdU-labeled cSCs within the tumor spheroids." (PMID 34360875, 2021). "Meanwhile, blocking CD36 on DCs with monoclonal antibodies recused their antigen presentation ability by MHC class II molecules, which improved CD4+ T cell priming and consequently boosted anti-tumor immune response." (PMID 34742349, 2021). "CD36 was the first TSP1 receptor identified to mediate its anti-angiogenic activity, and peptide mimetic drugs derived from a sequence in the second TSR repeat of TSP1 that binds to CD36 have been developed to inhibit tumor angiogenesis." (PMID 33925464, 2021).
tumor (continued). "Mirroring this increase in cells expressing M1 markers, the co-culture with SKOV3-R2+ cells opsonized with 3C23K-CHO and murlentamab decreased the proportion of M0 MDMs expressing CD163, CD36 and CD206, three M2 markers involved in TAM tumor promoting and immunosuppressive functions." (PMID 33924378, 2021). "We found that the expression levels of Lpl and Cd36 were equivalent in c-Myc/MCL1/Cre and c-Myc/MCL1/pCMV tumor samples, indicating the lack of a compensatory induction of the Lpl/Cd36 axis as a response to Fasn depletion in c-Myc mice." (PMID 33187130, 2020). "Therefore, taken together, our data suggest that upregulation of pAkt and survivin are potential mechanisms by which CD36 promotes CRC cell proliferation and tumor growth." (PMID 32850342, 2020). "Inhibition of STAT3 or STAT5 signaling or genetic deletion of fatty acid translocation enzyme CD36 inhibited activation of oxidative metabolism and induction of immunosuppressive function in tumor-invasive MDSCs, leading to CD8+ T-cell-dependent tumor growth delay." (PMID 33027968, 2020). "The scavenger receptor CD36 also participates in the internalization of long chain fatty acids and is highly expressed in tumor, but not normal, tissues." (PMID 33083663, 2020). "CD36 (p value < 2.22e-16), CPA3 (p value < 2.22e-16), NFATC1 (p value = 9.1e-08), and RASGRP2 (p value < 2.22e-16) were highly expressed and SLC2A3 (p value = 0.0015) was lowly expressed in tumor samples." (PMID 32908876, 2020). "Targeting CD36 with antibodies successfully depleted pro-tumor Tregs and improved tumor clearance without inducing autoimmunity." (PMID 33086598, 2020). "Meanwhile, RCC tumor cells showed remarkable increases in membranous FATP4 and CD36 and a decrease in ACSL1, indicating that RCC cells are metabolically different from normal cells and prefer the mechanism of fatty acid uptake from extracellular sources during tumorigenesis." (PMID 31089396, 2019). "Beyond fueling tumor metastasis and therapy resistance by enhancing lipid uptake and FA oxidation, CD36 attenuates angiogenesis by binding to TSP-1 and thereby inducing apoptosis or blocking the vascular endothelial growth factor receptor 2 pathway in tumor microvascular endothelial cells." (PMID 31410189, 2019). "GC patients with deep tumor invasion (T3 and T4), high pStage (stages III and IV) and more positive lymph nodes (>5) had significantly higher expression of CD36 than those with superficial tumor invasion (T1 and T2), low TNM stage (stages I and II) and fewer positive lymph nodes (≤5)." (PMID 31410220, 2019). "Accumulating evidence has confirmed that CD36, a cell surface receptor of FAs, allows cells to take up lipids from the extracellular microenvironment and promotes FA oxidation (FAO) to produce ATP potentially energizing tumor progression and metastasis." (PMID 30717785, 2019). "Overexpression of membranous FATP4 and CD36 combined with reduced cytoplasmic expression of ACSL1 might be a tumor-specific feature of RCC, contributing to the tumorigenesis and tumor progression." (PMID 31089396, 2019). "Weak or absent CD36 expression was seen in almost two-thirds tumor samples examined, whereas almost all normal specimens showed strong CD36 signal." (PMID 31484922, 2019). "Both CD36 and FATP4 revealed higher membranous expressions in RCC tumor cells than in normal cells." (PMID 31089396, 2019). "The authors reported CD36 expression on some, but not all tumour cells, as well as downregulation of CD36 expression on endothelium of neovessels, presumably due to repressed CD36 gene transcription via PDK1-FOXO1 activation by lysophosphatidic acid." (PMID 30069479, 2018). "Direct targeting of CD36 in tumour pathology has not yet been addressed in cancer-related clinical trials." (PMID 30069479, 2018). "COMP induced CD36-dependent activation of MEK/ERK and PI3K/AKT, and a panel of tumor-promoting factors, including EMT makers, MMP-2/9, Slug and Twist, so as to promote its tumor-promoting effects." (PMID 30231922, 2018).
tumor (continued). "Blocking lipid uptake with anti-CD36 antibodies in metastasis-initiating cells inoculated in mice successfully prevents metastasis initiation but not primary tumor formation." (PMID 29907133, 2018). "Overexpression of CD36 (CD36+) increases fatty acid uptake, significantly increasing the rate of lymph node metastasis, while the absence of CD36 decreases tumor metastasis." (PMID 29914089, 2018). "Western blotting revealed that FASN protein expression was elevated in CRC tissues, while real-time PCR and Western blotting indicated that FABP1, CD36 and Caveolin-1 mRNA and protein levels were reduced in CRC, potentially due to the reduced availability of exogenous lipids for the tumor." (PMID 28938608, 2017). "Interestingly, LPA/PKD-1 signaling suppresses CD36 transcription and reprograms MVECs for arteriogenic gene expression via a nuclear HDAC7-FoxO1 complex, implicating microvascular remodeling and tumor arteriogenesis." (PMID 27200349, 2016). "Cd36 is a scavenger receptor for oxidized low-density lipoprotein (LDL) found on the surface of myeloid cells, erythrocytes, endothelium and adipocytes in the tumour microenvironment." (PMID 25633981, 2015). "In addition, PPAR-γ agonists upregulate the expression of CD36, a TSP-1 receptor, which in turn promotes TSP-1 expression and inhibits tumor angiogenesis." (PMID 24348828, 2014). "Expression in U87-MG and U118 cell lines, PA-NAV, PA-GAS and PA-PET initial tumor specimen and in the excised tumor of the case report: we quantified the ICAM1, CRK, CD36, and IQGAP1 mRNA expression in our in vitro models and in the surgical specimen of the case report." (PMID 24252689, 2013). "In our study, we also found that CD36 was down-regulated in NSCLC tumor tissue, which could indicate an adaptation of tumor cells reduce sensitivity to TSP-1 and TSP-2-mediated apoptosis." (PMID 22509397, 2012). "In summary, we showed in these studies that modulating tumor cell expression of TSR proteins or expression in the non-transformed tumor microenvironment of CD36 or HRG had significant impact on tumor angiogenesis and tumor growth." (PMID 22808089, 2012). "Recent studies have shown that tumor infiltrating CD8+ T cells exhibited an upregulation of CD36 expression compared with T cells in normal tissues from the same patient and the cholesterol in the TME contributed to upregulating CD36 expression on CD8+ T cells." (PMID 40064873, 2025). "Compared with untreated controls, tumour-bearing mice treated with navarixin—an orally bioavailable small-molecule antagonist of CXCR1/2—or with thrombospondin-1 (TSP-1), which simultaneously blocks CD47 on tumour cells and CD36 on macrophages, presented significantly reduced tumour volumes." (PMID 41163221, 2025). "In addition, CD36 mediates the uptake of FAs by tumor-infiltrating CD8+ T cells, inducing LPO and ferroptosis, resulting in reduced tumor-toxic cytokine production and impaired anti-tumor immunity." (PMID 41421797, 2025). "Similarly, coupling CD36 inhibition with FASN blockade may restrict both exogenous and endogenous lipid supply, collectively reprogramming the tumor microenvironment toward an immune-responsive state." (PMID 41312365, 2025). "Furthermore, in the TME, cystine consumption by tumor cells disrupts the cystine/glutamate exchange in CD8+ T cells, leading to increased CD36 expression, fatty acids uptake, lipid accumulation, abnormal ROS production, and ultimately T cell exhaustion and ferroptosis." (PMID 40760119, 2025). "The integrin-mediated control of angiogenesis and metastasis axis confirms the role of integrins (especially αvβ5) and non-integrin adhesion receptors (e.g., CD36) in tumor angiogenesis, vasculogenic mimicry, and metastatic dissemination, particularly to the lungs." (PMID 41008880, 2025).